LUM (lumican)
Diseases named in the same sentence as LUM in open-access papers (continued):
Sharing a sentence is not in itself a finding about the gene and the disease.
cancer (continued). "LUM was expressed in the cell membrane and cytoplasm of carcinoma cells 3(60%) of 5 CCA cases." (PMID 31417643, 2019). "To determine if knockout of functional lumican gene could specifically change cancer cell function, we introduced lumican gRNAs CRISPR/Cas9 plasmid (0.25 ~ 1 μg/ml) into A549 and H460 cells for 48 h." (PMID 29549325, 2018). "Moreover, the overexpression of lumican has been found to affect the growth and invasion inhibition of malignant tumors cells." (PMID 29549325, 2018). "The aim of this study was to verify whether the expression of the analysed LUM gene and protein that was observed in tissue culture cell lines could also be confirmed in real cancer patient tissues." (PMID 29088800, 2017). "Lumican might have a dual role in cancer cells and stromal cells with opposite effects on cancer progression." (PMID 28481899, 2017). "In this study, it has been shown for the first time in the literature that lumican plays an important anticancer role in the transformation of epithelial cells in mesenchymal phenotype, which constitutes a key factor in the metastasis of cancer." (PMID 28332606, 2017). "In addition, genes potentially regulating lumican include HMGA2, an oncogene that is highly expressed in about 50% of carcinomas, which can downregulate LUM expression by directly binding its promotor region." (PMID 28481899, 2017). "However, recent studies have shed light on newly identified tissue-specific properties of both DCN and LUM in normal tissues and in the malignant cancer microenvironment." (PMID 26230845, 2015). "Furthermore, the expression of lumican has previously been shown to have a restrictive role in the progression of several other cancer types as well as being correlated with better survival, illustrating the potential anti-tumorigenic effect of this ECM shell-like structure on SHH MB." (PMID 36631900, 2023). "Thus, LUM may enhance cancer growth through integrin β1 activating the β-catenin/focal adhesion kinase (FAK)." (PMID 36076905, 2022). "Notably, lumican enhanced 14 signaling pathwayspotentially correlated with this cancer progression." (PMID 34572532, 2021). "However, lumican was also shown to actually facilitate cancer growth." (PMID 34638415, 2021). "Therefore, reduced lumican expression by cells BM-MSCs may facilitate cancer cells’ escape from chemotherapy and immune surveillance and support leukemia relapse." (PMID 34572532, 2021). "Additionally, LUM may mediate focal contact formation, cytoskeleton remodeling and cell migration by binding to the cancer cell membrane via receptors such as integrins." (PMID 34590603, 2021). "Lumican, a member of a class II family of small leucine-rich proteoglycans, is highly upregulated in different cancer types, especially pancreas, breast, and cervical cancer, and affects the proliferation, migration, and adhesion of cancer cells through a variety of mechanisms." (PMID 31406961, 2019). "This could be due to lumican's suppressing effects on cancer cells through regulating ER functions." (PMID 29881724, 2018). "To clarify whether N-glycosylation, reported in many cancers and cancer cell lines, could also be responsible for the increased mass of LUM, we performed digestion with PGNase F. Between different LUM bands, we observed the disappearance of those with molecular masses of 100 kDa and 50 kDa." (PMID 29088800, 2017). "Thus, alteration of lumican expression are supposed to be correlated to cancer spreading." (PMID 25961303, 2015). "In addition, KEGG pathway analysis further confirmed that Lumican could regulate the TGF‐β signaling pathway via the keratan sulfate proteoglycan, which is associated with extracellular matrix in proteoglycan in cancer KEGG pathway, highlighting its potential role in TMJOA progression." (PMID 40125663, 2025). "LUM is a common ECM component that organizes the collagen matrix and influences cell proliferation signals in cancer." (PMID 40789825, 2025).
cancer (continued). "Despite this, they retained strong expression of core stromal markers such as DCN, VIM, LUM, and IGFBP7, which were consistently observed across both ex vivo and in situ fibroblasts compared to the epithelial cancer cells." (PMID 41198614, 2025). "STAT5A signaling, CSPG4, MMP-1, MMP-3, MMP-8, MMP-9, and LUM are all involved in cancer cell migration, invasion, and metastasis, while PKM supports the growth and survival of cancer cells by favoring aerobic glycolysis." (PMID 39201614, 2024). "Our ECM panel for PCC-NOS includes SLRPs like LUM, BGN, PRELP, and ASPN, which exhibit dual functions in cancer." (PMID 39305996, 2024). "We identified a progenitor cell population highly enriched in samples from invasive and chemo-resistant carcinomas, characterized by a well-defined multigene signature including APOD, DCN, and LUM." (PMID 38466528, 2024). "Lumican is an SLRPG, and studies have shown that Lumican regulates cancer cell proliferation, invasion, and metastasis through different mechanisms." (PMID 37894512, 2023). "The “Proteoglycans in cancer” pathway was also exclusively enriched in AA-SScL fibroblasts, driven by the upregulation of IGF2, DCN, LUM, COL1A1, COL1A2, and the receptors KDR and TLR4." (PMID 36835058, 2023). "Previous studies reported that LUM is the most abundant protein polysaccharide in BRCA, and LUM expressions in cancer cells are high." (PMID 37692065, 2023). "LUM is involved in multiple cancer-related processes, including EMT, and the impact of LUM in cancer aggressiveness is cancer-type specific." (PMID 36358747, 2022). "From the lncRNA-mRNA pathway network, PYCARD, RIPK2, and CASP1 were found to be significantly enriched in the NOD-like receptor signaling pathway, whereas MAP2K2, LUM, RPS6, PDCD4, TWIST1, and HIF1A were significantly enriched in proteoglycans in cancers." (PMID 36619896, 2022). "Lumican (57 kDa) is able to inhibit MMP-14 activity and to protect collagen degradation contributing to attenuation of MMP-14-dependent cancer cell migration and invasion." (PMID 34638415, 2021). "DCN, BGN, LUM and fibromodulin (FMOD) are the most reported members of SLRPs involved in cancer progression." (PMID 34888227, 2021). "For the case of fibroblast cells associated dataset, the most significant pathway obtained was Proteoglycans in cancer (p value 1.2 × 10−3) (CD63, DDX5, DCN, LUM, ITGB1)." (PMID 34071236, 2021). "Thus, a basal expression of lumican might play a vital role for cancer cell survival." (PMID 29549325, 2018). "High LUM protein levels in cell culture media can bind TOP molecules and inhibit their penetration into cancer cells." (PMID 29088800, 2017). "To date, a single study has examined lumican expression in EOC, demonstrating reduced stromal expression and suggesting a possible role in cancer aggression." (PMID 26579497, 2015). "To further confirm the conclusion of genetic MR analysis, we compared the expression of STX7 and LUM in paired human cancer specimens and adjacent non-cancerous tissues based on TCGA by GEPIA 2.0." (PMID 40789825, 2025). "At the same time, multiple collagen-related genes (COL6A2, COL3A1, COL4A1, and COL4A2) in the MSC-2 cluster were upregulated in bone metastases, which is consistent with our observation of IGFBP3, TAGLN, LUM, COL6A1, COL6A2, and COL3A1 in pan-cancer in Fig. (1d)." (PMID 39156727, 2024). "Lumican-IL-2 and lumican-IL-12 also enhanced combined therapies such as therapeutic antibodies, cancer vaccines and CAR-T therapy without systemic toxicity." (PMID 37692860, 2023). "Lumican promotes cell proliferation in human trophoblast cells, inhibits bone formation and osteoclast function via Akt and ERK signalling and exerts both pro- and anti-proliferative effects on a number of cancers." (PMID 36457256, 2022). "Taken together, these results suggest that MAP2K2, LUM, RPS6, PDCD4, TWIST1, and HIF1A may play important roles in DMD pathophysiology by regulating the MAPK pathway and proteoglycans in cancer." (PMID 36619896, 2022).
cancer (continued). "Relative expression levels of Lumican in seven cancer cell lines were compared with the nontumor cell line (NE3) after they were normalized by the expression of β-actin and calculated by the 2−ΔΔCt method by qPCR." (PMID 36361971, 2022). "In our proposed DMD-related lncRNA-mRNA pathway networks, PYCARD, RIPK2, and CASP1 were significantly enriched in the NOD-like receptor signaling pathway, whereas MAP2K2, LUM, RPS6, PDCD4, TWIST1, and HIF1A were significantly enriched in proteoglycans in cancers." (PMID 36619896, 2022). "Analysis at SEM demonstrated that lumican treatment reduces the aggressiveness of both Mock-B16F1 and Snail-B16F1 cells by reducing the cytoplasmic protrusions and microvilli which are related to cancer cells’ aggressiveness." (PMID 33917849, 2021). "Thus, lumican-overexpressing murine fibrosarcoma (MCA102) and pancreatic adenocarcinoma (Pan02) cells providesmaller tumors in vivo compared withwild-type cancer cells." (PMID 34572532, 2021). "We observed that hypoxia significantly reduced lumican expression and secretion from pancreatic stellate cells but not cancer cells." (PMID 31406961, 2019). "MMP2, IGF2, DCN, LUM and TWIST are involved in proteoglycans in cancer pathway." (PMID 30576338, 2018). "In SCC, LUM expression was found in stromal tissue but not in the cytoplasm of cancer cells, which was correlated with vascular invasion." (PMID 29088800, 2017). "The aim of this study was to determine whether the SLRPs decorin (DCN) and lumican (LUM) are recruited in cell plasticity and microenvironmental adaptation of differentiated cancer cells induced towards stem-like phenotype." (PMID 26230845, 2015). "Some other proteoglycans such as aggrecan, neurocan, brevican, biglycan, lumican, glypicans, fibromodulin, agrin, collagen XVIII, NG2, and serglycin are also involved in cancer progression, but their expression and functional role have not yet been investigated in prostate cancer." (PMID 23691363, 2013). "Similarly, proteins involved in the inhibition of cancer invasion are highly upregulated (fold change ≥ 1) in NVA-AA-treated MDA-MB-231 cells, e.g., lumican (LUM), along with proteins involved in vesicular trafficking, e.g., Rab GDP dissociation inhibitor beta (GDI2)." (PMID 37719007, 2023). "Compound 91b1 dose-dependently downregulated the relative expression of Lumican in KYSE150 cells, suggesting that quinoline compound 91b1 probably induces an anticancer effect by downregulating the expression of Lumican, modulating its upstream or downstream signaling pathway in cancer cells." (PMID 36361971, 2022). "Furthermore, the mechanism strongly downregulates lumican secretion through post-transcriptional regulation of pancreatic stellate cells, not cancer cells." (PMID 34572532, 2021). "The small leucine-rich proteoglycan lumican, for instance, inhibits and even reverses some of the characteristics of EMT, such as invadopodia formation, suggesting lumican as a marker for staging of several cancers and the development of cancer drugs based on lumican." (PMID 33379400, 2020). "These peptides might be putative cancer biomarkers but, to our knowledge, there are up to now no data in the literature describing lumican-derived peptides as biological markers in cancer." (PMID 32351878, 2020). "However, such approach mainly depending on lumican ectopic expression from inoculated cancer cells is not relevant in understanding the contribution of host lumican." (PMID 28794454, 2017). "Interestingly, in spite of their pan-inhibitory properties against receptor tyrosine kinases (RTKs) and cancer growth pathways, the “guardian from the matrix” decorin (DCN) and lumican (LUM) SLRPs could exert anticancer effects in vivo and in vitro." (PMID 26230845, 2015).
cancer (continued). "Furthermore, differentially quantified proteins (such as PGS2, UGDH, ASPN, LUM, COEA1, and PRELP) were found in comparisons of healthy and cancer breast tissues, suggesting potential utility of the All-in-One pipeline for the emerging application of proteomic cancer sub-typing." (PMID 36937585, 2023). "Importantly, the fact that we did not detect any mRNA of cancer‐specific genes (AZGP1 and KRT19), nor of CAF‐specific genes (LUM and DCN), confirmed the absence of non‐endothelial RNA contamination." (PMID 40348600, 2025).
infection (7 papers, 2013 to 2024). The state of being infected such as from the introduction of a foreign agent such as serum, vaccine, antigenic substance or organism. "Taken together, the results indicate that lumican facilitates development of an innate immune response at the earlier stages of infection and lumican deficiency leads to poor bacterial clearance and resolution of corneal inflammation at a later stage." (PMID 23358433, 2013). "LUM and the other SLRPs act as danger signals and signal through the innate immune system to counter infections and fine-tune inflammation and regulation of autoimmune diseases." (PMID 38474072, 2024). "Our in vivo results clearly showed that lumican knockdown decreased muscle mass in exercised mice, despite the poor infection efficiency (40%) afforded by AAV6-lumican shRNA." (PMID 36077426, 2022). "Alternatively, lower lumican may lead to disruption of the collagen and fibril assembly pathways as a consequence of infection." (PMID 35842456, 2022). "Mature IL-1β had increased dramatically in the cornea by 24 h of infection, and this was not significantly affected by lumican deficiency." (PMID 23358433, 2013). "To determine if the decrease in CXCL1 at the later stages of infection was due to transcriptional differences in regulation in the absence of lumican, we determined Cxcl1 expression by real time qRT-PCR in total RNA extracted from Lum+/− and Lum−/− infected corneas." (PMID 23358433, 2013). "Moreover, endocytosed lumican colocalizes with TLR4 and LPS and promotes endosomal induction of type I interferons, in explaining the effects of the extracellular matrix on infection and immunity." (PMID 35844488, 2022). "Three hrs after infection TNF-α was close to baseline in both genotypes, indicating that early innate immune response from resident corneal cells was not affected by lumican-deficiency." (PMID 23358433, 2013).
bacterial infection (2 papers, 2013 to 2021). "We have minimally examined lumican functions in a live bacterial infection setting in a lung infection model where the Lum−/− mice showed increased bacterial persistence and poor host survival." (PMID 23358433, 2013). "For example, lumican, one of the core proteins of corneal keratin sulfate proteoglycan, is required for inducing adequate increases in neutrophil infiltration to counter external stress induced by bacterial infection or tissue injury." (PMID 33782532, 2021). "Lumican-deficient (Lum−/−) mice and macrophages are impaired in TLR4 signals; raising the possibility that lumican may regulate host response to live bacterial infections." (PMID 23358433, 2013).
cardiac diseases (2 papers, 2020 to 2023). "Key myocardial proteins, lumican, lysyl oxidase (LOX) isoenzymes and TGF-β isoforms are critical for the development of fibrosis and cardiomyocyte hypertrophy in various cardiac diseases." (PMID 37443910, 2023). "As lumican has been reported to promote myocardial ECM remodelling through upregulating LOX and TGF-β in cardiac diseases, the relationship between the lumican gene and these potential downstream targets was assessed." (PMID 37443910, 2023). "Together with another group of four proteins from the SLRP family, namely fibromodulin (FMOD), osteomodulin (OMD), osteoglycin (OGN) and lumican (LUM), the importance of extracellular remodeling processes in heart disease is emphasized." (PMID 32670412, 2020). "Importantly, lumican and LOX isoenzymes can be upregulated by the release of inflammatory cytokines from leucocytes and altered mechanical stress, both of which are important components of many cardiac diseases, including HCM." (PMID 37443910, 2023).
cardiovascular disease (2 papers, 2013 to 2023). "SLRPs, including LUM, BGN, and DCN, are all crosslinking regulators and are shown to play a role in ECM remodeling and fibrosis in different mouse models of muscular and cardiovascular diseases." (PMID 38130476, 2023).
immune system diseases (1 paper, 2018). "DEGs that enriched to “immune system diseases” played critical roles in cell-matrix communication (THY1, LVRN, LUM, TIMP3, SPOCK1, LGALS3BP, FAT2, and SERPINE2) as well as inflammation (IL1R2, CD22, PTGES, TNFSF10, IL2RB, C3, SERPING1, and IL-17RE)." (PMID 30131724, 2018).
inflammation (1 paper, 2022). Aberrant reaction of the microcirculation characterized by movement of fluid and leukocytes from the blood into extravascular tissues. "Moreover, Masson’s trichrome staining further confirmed that lumican knockdown alleviated fibrotic lesions in the early phase of lung inflammation in LPS-challenged mice." (PMID 36059026, 2022).
lip (1 paper, 2025). "Other proteins proposed as biomarkers of poor prognosis include cleft lip and palate transmembrane protein 1-like protein (CLPTM1L) and lumican (LUM)." (PMID 40650278, 2025).
LUM also shares sentences with these, for which no sentence is quoted: esophageal squamous cell carcinoma (4 papers); adenocarcinoma (3); connective tissue disorder (3); myocardial infarction (3); colon adenocarcinoma (2); cornea plana (2); dilatation (2); Duchenne muscular dystrophy (2); keratoconus (2); acute myocardial infarction (1); Alzheimer disease (1); amyotrophic lateral sclerosis (1); aortic aneurysm (1); aortic stenosis (1); autoimmune disease (1); Behçet's syndrome (1); Bowen's disease (1); brain cancer (1); cardiac arrhythmia (1); cardiac congestive/cardiac failure (1); colorectal adenoma (1); congenital heart anomaly (1); corneal dystrophies (1); corneal ulcer (1); coronary arterial disease (1); dermatosis (1); disc degeneration (1); ductal adenocarcinoma (1); Ehlers-Danlos syndrome (1); emphysema (1).
A further 33 diseases each share a sentence with LUM in 1 paper.